MET (MET proto-oncogene, receptor tyrosine kinase)
Diseases named in the same sentence as MET in open-access papers (continued):
Sharing a sentence is not in itself a finding about the gene and the disease.
tumor (continued). "Some of these genes, which interfere with tumor cell growth/differentiation/migration/invasion (such as MYC, MET, PROM1, and PTK2), induce hypoxia (such as ARNT2, HIF3A, TGB2, MMP2, and POSTN) and genes regulating transcription via acetylation were downregulated upon pembrolizumab treatment." (PMID 32616706, 2020). "To assess the expression level of ANTXR1 in patients with GC, we compared the expression level of ANTXR1 in non-paired tumor and adjacent tissues and paired samples, and the MET was considered as positive control while ACTB was considered as negative control." (PMID 33385012, 2020). "Further analysis of tumor tissues, confirmed the in vitro results that when compared to the vehicle-treated group, SF + MU treatment downregulated phospho-MET, and CD44 levels in EV tumors, but not in A9 tumors." (PMID 32427869, 2020). "First, we evaluated the enrichment potential of the CellSearch® and Parsortix systems, using preserved blood samples from healthy controls spiked with six human tumor cells (LNCaP, NCI-N87, Hs746T, AU565, SNU-5, and C32), representative of the variability of MET CN and MET expression." (PMID 32102486, 2020). "In addition, it also inhibited the growth of MET and AXL‐independent SNU719 cells at higher but clinically relevant doses through tumor microenvironment." (PMID 34766112, 2020). "Furthermore, in vivo experiment in AGS xenograft mouse model, co‐inhibition of c‐MET and PARP decreases tumour volume mass." (PMID 32686903, 2020). "Other second-line treatments may be proposed upon tumor progression for cases with genomic alterations in RET, MET, NTRK, HER2, or other genes, but the patient is also included into a clinical trial most of the time, at least in France." (PMID 32294880, 2020). "We report here a clinically relevant orthotopic mouse model of ERBB2+ BC that spontaneously metastasizes to brain and demonstrates that targeting the c-MET/ERBB1 axis with a combination of cabozantinib and neratinib decreases primary tumor growth and prevents brain metastasis in ERBB2+ BC." (PMID 33019652, 2020). "Therefore, we investigated the possible tumor-suppressing functions of Brg1 in mice and found that deletion of Brg1 cooperates with activated Ras/MAPK signaling (via either c-MET or NRASV12 overexpression) to promote HCC development in mice." (PMID 32019910, 2020). "Finally, we focused on patient 21, with a pT3N0 intestinal histologic subtype tumor arising from the gastric antrum characterized by gains of EGFR, MYC (OMIM 190080) KRAS, MET, and PIK3CA by OncoScan (eFigure 4C in the Supplement)." (PMID 32338752, 2020). "Recent studies have shown that under hypoxic conditions, tumor cells developed resistance to MET inhibitors (PHA-665752 and SU11274) and, interestingly, could recover their sensitivity to MET-TKI when normoxia was restored." (PMID 32435640, 2020). "Its upregulation could stimulate tumor migration and growth through miR-338/MACC1/MET/AKT or ERK pathway by sponging miR-338." (PMID 32083078, 2020). "Importantly, our findings indicate that combined pharmacological inhibition of MET and CDK4/6 is a feasible strategy able to improve tumour growth inhibition in mice, indicating the potential of this combination for clinical use." (PMID 31296956, 2019). "Apart from MET amplification, detected in one tumor, we have not been able to identify other already known mechanisms responsible for the lack of responsiveness to osimertinib." (PMID 31138260, 2019). "It has lately been suggested that hepatocyte growth factor (HGF) secreted by PSCs and the presence of HGF’s receptor c-MET on PDAC cells, may play a major role in the tumor promoting effect of PSCs on PDAC cells." (PMID 31072019, 2019).
tumor (continued). "A common reason is that in populations with EGFR, BRAF, MET, ALK and other gene mutations, it is not easy to produce new antigens of tumours, and the tumour mutation load is lower." (PMID 30862891, 2019). "The co-administration of foretinib and lapatinib effectively inhibited both MET and HER2 phosphorylation, enhanced inhibition of cell proliferation and xenograft tumor growth by inducing apoptosis, and significantly enhanced mouse overall survival, overcoming single agent resistance." (PMID 31772236, 2019). "Of note, gene amplification of other receptor tyrosine kinases (RTKs) such as platelet-derived growth factor receptor (PDGFR) and MET was not noted in any of the tumour samples." (PMID 30644426, 2019). "In each TNM stage or tumor histological grade, there were more patients who had a greater expression of c-MET in the tumor tissue than in the non-tumor tissue." (PMID 30850583, 2019). "The results of this study indicate that c-MET and RUNX3 are differentially expressed in GCs compared with normal adjacent gastric mucosa and found a correlation between low RUNX3 levels and c-MET overexpression and tumor recurrence." (PMID 30871613, 2019). "qPCR assay was used to evaluate the expression of c-MET and CTLA-4 in primary NSCLC tumor tissues." (PMID 29187584, 2019). "In AKT/c-MET mice, tumor nodules were diffused and colliding, with no surrounding capsules; as a consequence, it was impossible to accurately count the surface tumor nodule number in these mice." (PMID 31277283, 2019). "The heterogeneous but co-existing distribution of these EGFR, MET, and PDGFRA gene amplifications suggests that glioblastoma may undergo a dynamic evolution during tumour progression that creates diversity within a single mass." (PMID 30736342, 2019). "The method used to determine c-MET (= single marker IHC) in the current study was not suited to discriminate metastasis initiating sub-clones from the rest of the tumor cells." (PMID 29463215, 2018). "The ALK/MET inhibitor crizotinib enhanced the anti-tumor effect of the mTOR-inhibitor rapamycin in a patient-derived MPM xenograft with co-activated ALK/mTOR: combined therapy achieved tumor shrinkage in 4/5 tumors and growth stagnation in one tumor." (PMID 29755689, 2018). "However, considerable evidence has demonstrated that EGFR blockade, or inhibition of other receptor systems such as HER2, MET and IGF-IR leads to enhanced or re-activated STAT3 activity and subsequent continued tumor progression." (PMID 30572654, 2018). "We studied a retrospective cohort of 160 consecutive surgically treated NSCLC patients with available frozen tumor samples for expression of EMT markers (CDH1, CTNNB1, CDH2, and VIMENTIN), inducers (TGFB1, c‐MET, and CAIX), and transcription factors (EMT‐TF:SNAI1, SNAI2, ZEB1, TWIST1, and TWIST2)." (PMID 29845746, 2018). "At cut off >5% of tumour cells with positive staining, 62%, 59%, 65% and 45% of the cases were EGFR, HER-2, HER-3 and HER-4 positive, and 3%, 22% and 48.3% of the cases were positive for EGFRvIII, c-MET, and CD44 respectively." (PMID 29731973, 2018). "A novel c-MET inhibitor DE605 plus sorafenib may effectively induce HCC cell apoptosis in vitro and suppress HCC tumor xenografts in vivo." (PMID 30360560, 2018). "Then we tested if NZ001, a novel ATP-competitive multi-targeted kinase inhibitor that simultaneously inhibits both MET and VEGFR2, could suppress both tumor growth and metastasis." (PMID 29712569, 2018). "For non-MET amplified HCC such as Huh7 tumors, impeding stromal angiogenesis through VEGFR2 inhibition (anti-angiogenesis effect) contributed to the dominant abrogation of tumor growth." (PMID 29712569, 2018). "When VEGF activity is genetically or pharmacologically inhibited, the resulting tumors were largely non-angiogenic, highly diffuse and the infiltrating tumor cells harbored high levels of phosphorylated (active) c-MET." (PMID 28821904, 2018).
tumor (continued). "We measured the proliferation of the IGROV1Res and OAW42Res tumor cell lines treated with increasing concentrations of GDC0032, in the absence or presence of inhibitors such as AEW541 (IGF1R inhibitor), PHA-665752 (MET inhibitor), MK2206 (AKT inhibitor), and others." (PMID 30237504, 2018). "MET activation is a universal mechanism that drives cell survival, invasion, and metastasis in many cancers and cooperates with the VEGFR pathways to promote tumor angiogenesis." (PMID 29892268, 2018). "We did not observe any similar effect of MET amplification on protein expression in other histological tumor types." (PMID 30442178, 2018). "At the molecular level, etoposide induced MET and STT3 downregulation in tumor cells." (PMID 29765039, 2018). "Furthermore, PDX (patient–derived tumor xenograft) model experiment showed that NZ001 had a significant inhibitory effect on tumor growth of HCC with MET-amplification and MET-overexpression, and also prolonged the survival of mice." (PMID 29712569, 2018). "Furthermore, the patient’s tumor harbored amplifications of BRAF, EGFR, MET, and CDK6, which provides a rationale for this tumor’s acquired resistance to the triple BRAF/MEK/CDK4&6 inhibitor treatment applied before sequencing." (PMID 30373609, 2018). "We applied PF-04217903, a selective MET signaling inhibitor, in the hepa orthotopic models, and found that PF-04217903 alone did not result in obvious alterations in tumor volume and metastasis compared with the controls." (PMID 29712569, 2018). "Concerning Sanger's sequencing, no mutation was observed by direct sequencing for exons 14 and 16–19 of the MET gene, neither in tumor samples nor in GSC lines." (PMID 28960893, 2017). "Different MET inhibition strategies are being developed such as HGF ligand or MET receptor inhibitions, particularly with crizotinib, which has shown efficacy in depleting tumor‐propagating stem‐like cells." (PMID 28960893, 2017). "Similar protein doses of 89Zr-OA-NBC and 111In-OA-NBC one-armed isotype controls for 89Zr-onartuzumab did not accumulate in tumour tissues, confirming the c-MET specificity of the 89Zr-onartuzumab signal." (PMID 28315949, 2017). "In VHL-negative xenograft models, treatment with the VEGFR-selective inhibitor axitinib reduces tumor growth and prolongs survival, whereas treatment with crizotinib, which inhibits MET but not VEGFR, is much less effective." (PMID 28247252, 2017). "Clinical trials using tivantinib, therefore, have not yet clarified the potential anti-tumor activity and feasibility of the MET inhibitor in ASPS." (PMID 28945796, 2017). "Many genes in these chromosome lesions, such as EGFR (amp 7p11.2), MET (amp 7q31.2), KRAS (amp 12p12.1), and CACNA2D2 (del 3p21.31), are known to be related to tumor invasion and metastasis." (PMID 28922552, 2017). "Recently, we determined that combined MET and EGFR inhibition was highly effective at abrogating tumor growth in patient-derived TNBC tumorgrafts and significantly decreased the variability in treatment response compared to monotherapy with MET or EGFR inhibitors." (PMID 28852500, 2017). "They showed that tumor uptake of 11C-SU11274 in c-MET-positive H1975 bearing mice (human NSCLC) was significantly higher than that in c-MET-negative H520 (human NSCLC) xenografts." (PMID 28485003, 2017). "This gene has been recently identified as an important factor in tumor cell proliferation, invasion and metastasis in several cancers such as Colon, HCC, Breast, Ovarian, etc. via the c-MET/HGF signalling pathway and is being evaluated as a potential therapeutic target." (PMID 29162051, 2017). "The identification of MET amplification in the patient’s tumor, a well-established mechanism of resistance to anti-EGFR therapy, led to the prescription of a combination of erlotinib and the MET inhibitor crizotinib." (PMID 29241554, 2017).
tumor (continued). "TNF-α, and IL-6 are produced in the microenvironment of the tumor as a result of the nonspecific inflammatory response, which appears to increase c-MET expression." (PMID 28404966, 2017). "Upregulation of c-MET in EGFR TKI gefitinib-resistant HCC827-GR6 xenografts was visualized with a 89Zr-labelled H2 cys-diabody and H2 minibody, with twofold higher uptake observed in resistant tumours." (PMID 28315949, 2017). "In squamous cell carcinoma resistant to PI3K inhibitors, dimerization of AXL with EGFR activates the PLCγ/PKC/mTOR pathway to sustain tumor progression [61••], and in mesenchymal ovarian tumors and cell lines, AXL dimerized with MET, EGFR, and HER2, leading to sustained ERK activation [62•]." (PMID 28251492, 2017). "In line with our in vitro findings of a negative control by TGF-β of c-MET activation, the two antigens were rarely present simultaneously in the same tumor specimen (n = 13)." (PMID 29238047, 2017). "This indicates that novel mechanisms, such as WNK1 activation, may contribute to prosurvival activity of HGF in MET-amplified NSCLC cells and maintain the tumor-promoting crosstalk between tumor cells and cancer- associated fibroblasts." (PMID 28968967, 2017). "Similar to both MMP-2 and c-MET, TIMP-1 positive cells were present around blood vessels as well as in areas of necrosis, and similar to MMP-2, cells expressing TIMP-1 were also observed in the tumor periphery." (PMID 28234925, 2017). "This strengthens the conclusion that the extra uptake in c-MET-upregulated HCC827ErlRes xenografts is indeed mediated by c-MET expression, and is not caused by possible variations in tumour size, blood pool tracer availability and permeability effects." (PMID 28315949, 2017). "Unfortunately, the low number of patients with EGFR mutant tumor exclude us from studying potential role of high MET expression as a potential negative predictive marker in first line EGFR TKI therapy." (PMID 28915692, 2017). "For this study we focused our analysis on adjacent normal (n=18) and primary tumor (n=73) cores contained within a TMA that was subjected to immunohistochemistry (IHC) staining to determine the relationship between c-CBL, MET, and phosphorylated MET (Y1230/34/35 and Y1003)." (PMID 27244893, 2017). "The Multiple Beam Search (MBS) algorithm learned interactions from data and discovered that hsa-miR-21, hsa-miR-10b, hsa-miR-448, and hsa-miR-96 interact with oncogenes, such as, CCND2, ESR1, MET, NOTCH1, TGFBR2 and TGFB1 that promote tumor metastasis, invasion, and cell proliferation." (PMID 28793339, 2017). "Cancer-associated fibroblasts are the main source of pro-HGF in the tumor microenvironment, therefore we tested whether inhibitors of pro-HGF activation can overcome fibroblast–mediated resistance to MET-targeted therapy." (PMID 28968967, 2017). "Furthermore, a recent gene expression profiling study in ASPS revealed that certain TKs (c-MET and VEGFR) were expressed in ASPS and related to the malignant features of the tumor cells." (PMID 28945796, 2017). "While Cabozantinib treatment initially led to reduced phosphorylation, pMET levels normalized after 9 days and presence of MET was not required for tumor growth." (PMID 27105539, 2016). "Using RNA in situ hybridization (RNA ISH) and immunohistochemistry (IHC), we show high MET mRNA but not protein levels in tumor budding foci at the invasive front of stage III CRC tumors." (PMID 27793046, 2016). "In tumor models, the MET CN detected by ddPCR was significantly different between the MET gene amplification and non-amplification groups according to FISH (mean: 15.4 vs 2.1; P = 0.044)." (PMID 26765781, 2016). "In tumor tissue, no statistically significant trend towards changes in c-MET phosphorylation upon cold ischemia was detected." (PMID 26742633, 2016). "His tumour was wild type for EGFR, KRAS and ALK, but did display MET positivity by IHC." (PMID 26883990, 2016).
tumor (continued). "IHC analysis of serial slices showed that tumor cells in bone lesions expressed CD105 and c-MET." (PMID 27322553, 2016). "Crizotinib, a MET inhibitor, did not impact on tumor growth at all in this model, but did suppress body weight gain." (PMID 27736957, 2016). "MET is an oncogene that, when activated by its ligand HGF, exhibits potent migration/invasion-inducing activity and is frequently expressed in OS and is strictly related to its aggressiveness, and found relevant for the pathogenesis of this tumor." (PMID 27851822, 2016). "Using RNA in situ hybridization (RNA ISH), we further showed that MET mRNA, but not protein levels, were significantly upregulated in tumor budding foci at the invasive front of a cohort of stage III CRC tumors (p < 0.001)." (PMID 27793046, 2016). "In particular, some of them are known to be up-regulated in tumor cells enhancing the aggressive nature of tumors (e.g. EFEMP1), promoting migration and invasion of cancer cells (e.g. GPC6) or acting as proto-oncogenes (e.g. MET)." (PMID 26918450, 2016). "However, an aberrant MET/HGF axis results in cell migration and survival and promotes tumor development and progression." (PMID 27013592, 2016). "Here we demonstrate that combined MET and EGFR inhibition with either MGCD265 and erlotinib treatment or crizotinib and erlotinib treatment were highly effective at abrogating tumor growth and significantly decreased the variability in treatment response compared to monotherapy." (PMID 27655711, 2016). "Our past miRNA studies of BC cells showed that clustered miRNAs (including miR-1/133a (targeting TAGLN2), miR-23b/27b/24-1 (targeting EGFR, MET, and FOXM1), and miR-195/497 (targeting BIRC5 and WNT7A)) act as tumor-suppressive miRNAs through their regulation of several oncogenic genes and pathways." (PMID 27072587, 2016). "It was observed that membranous MET immunoreactivity is either constant across the cancer (uniform negative or positive staining) or differs between the tumor center and periphery (variable staining)." (PMID 26909606, 2016). "Moreover, KAI1 is able to be bind to c-MET to form a complex or quench the activation of HGF, thus preventing the activation of MACC1 to inhibit the migration of tumor cells." (PMID 27793161, 2016). "Our previous study reported miR-206 could also target 3′-UTR of MET and BCL2, and activate apoptosis, inhibit tumor cell proliferation, migration and colony formation in NSCLC cell lines (A549 and SK-MES-1)." (PMID 26909600, 2016). "In contrast, SRI 31215 prevented fibroblast-induced MET activation and signaling in tumor cells, but did not prevent MET activation induced by active HGF." (PMID 27121052, 2016). "A limitation of our study was the small sample size of our pilot study, and a larger prospective study is planned to assess c-MET expression in stage II/III CRC, using both MET RNA ISH and IHC analysis of tumor budding foci, invasive front and central tumor and correlate with patient outcome." (PMID 27793046, 2016). "In LAC cells with acquired resistance to Epidermal Growth Factor Receptor Tyrosin Kinase Inhibitor (EGFR-TKI), we found that a part of tumor cells were much more sensitive to HH or HGF/MET inhibitors, suggesting an oncogenic addiction shift from EGFR to HH and HGF/MET pathways." (PMID 27015549, 2016). "Other oncogenic pathways, such as EGFR and TGF-β, appear to be involved in tumor progression independent of MET signaling." (PMID 27013592, 2016). "In conclusion, our results clearly demonstrated that TAS-115 markedly inhibited tumor growth via VEGFR-kinase blockade, and also suppressed bone destruction, possibly through VEGFRs/MET/FMS-kinase blockade, which resulted in potent efficacy of TAS-115 in the A549-Luc-BM1 bone disease model." (PMID 27736957, 2016).